TNF (tumor necrosis factor)
Diseases named in the same sentence as TNF in open-access papers (continued):
Sharing a sentence is not in itself a finding about the gene and the disease.
Sepsis (continued). "Therefore, TNF is often associated with the inflammatory state of sepsis." (PMID 38066783, 2023). "Furthermore, the low serum albumin level in the acute phase of sepsis may be due to the inhibition of the albumin gene caused by TNF-α overexpression during inflammation." (PMID 35453552, 2022). "Gabexate has a short half-life of approximately 1 min, necessitating continuous infusion, and may be more effective in sepsis-associated DIC than in aortic aneurysm-associated DIC because it also inhibits the release of tumor necrosis factor-α (TNF-α) and inhibits cytokine release from macrophages." (PMID 35163216, 2022). "During sepsis, the pathogen-associated molecular patterns trigger systemic inflammatory responses, leading to an excess production of proinflammatory cytokines that are responsible for coagulopathy, such as interleukin (IL)-1, IL-6, and tumor necrosis factor-α (TNF-α)." (PMID 36431172, 2022). "In addition, we further explored whether our HLA classifier was associated with the ratio of IL10/TNF in sepsis." (PMID 35685286, 2022). "Interestingly, increased circulating levels of TNF-α and IL-6 are considered the main features of the inflammatory response associated with sepsis and play a key role in the pathophysiology of severe sepsis." (PMID 35163089, 2022). "These associations between pre-sepsis immune dysfunction and mortality are supported by studies showing that sepsis impairs production of IL-1, IL-6, TNF-α, IL-12, and IFN-γ and suggesting that this sepsis-induced immunosuppressive state may be augmented by release of IL-4 and IL-10." (PMID 35271683, 2022). "sTNFR-1 is the circulating form of the membrane-bound receptor which is essential for TNF signaling that results in both inflammation and endothelial dysfunction and we and others have shown that sTNFR-1 is highly associated with organ dysfunction and death in sepsis and other forms of ARDS." (PMID 33874973, 2021). "Their higher levels of IL-6 and TNFα and damage could increase their susceptibility to sepsis." (PMID 33788832, 2021). "Sepsis and the subsequent inflammatory and the so-called “cytokine storm” may also contribute to encephalopathy with IL-6, IL-8, IL-10, and tumor necrosis factor α (TNFα) being implicated in confusional states." (PMID 32751841, 2020). "In recent years, studies have suggested that sepsis-induced cardiac dysfunction, the major cause of sepsis mortality (70–90%), is caused by myocardial apoptosis mediated by the MyD88 signal pathway that activates and over-expresses a variety of pro-inflammatory cytokines, including TNF-α and IL-6." (PMID 32423469, 2020). "Lnc‐MALAT1 was positively correlated with Scr (r = .254, P < .001), CRP (r = .494, P < .001), TNF‐α (r = .387, P < .001), IL‐1β (r = .330, P < .001), IL‐6 (r = .431, P < .001), and IL‐8 (r = .420, P < .001), while negatively associated with albumin (r = −.153, P = .033) in sepsis patients." (PMID 32309886, 2020). "A cohort study involving children with sepsis and healthy ones revealed that the expression levels of miR-223 and miR-146a substantially increased; the increase in miR-223 level was positively associated with a high level of tumor necrosis factor-α, disease severity, and poor prognosis." (PMID 31088429, 2019). "In murine CLP-sepsis, human adipose-derived mesenchymal stem cells were able to modulate sepsis by downregulation of Th1-cell responses, associated with lower levels of pro-inflammatory cytokines (TNF, IL-1β, IL-6, IL-12, IFNγ) and higher levels of anti-inflammatory IL-10 derived from macrophages." (PMID 31114571, 2019). "Thus, whilst haemolysis (as measured by low HPX, reflecting cumulative exposure to haem) and IL-10 are both associated with markers of inflammation (IL-6, TNFα, and G-CSF), IL-10 is most closely associated with raised HO-1 in sepsis patients at the time of admission." (PMID 30046137, 2018).
Sepsis (continued). "This can lead to the release of a variety of inflammatory mediators such as IL-1 and TNF-α, which are associated with increased migration and permeability of endothelial cells in sepsis and may be related to the increase in mononuclear macrophage transmembrane migration." (PMID 29967433, 2018). "Thus, our meta-analysis is a relatively objective evaluation of TNF-α SNPs in sepsis risk." (PMID 29340067, 2017). "Of the 34 publications, 30 (33 studies) examined correlations between the TNF-α −308 A/G polymorphism and risk of sepsis, 8 examined correlations between this polymorphism and risk of septic shock, and 16 examined correlations between this polymorphism and risk of sepsis-related mortality." (PMID 29212277, 2017). "Furthermore, this study found that, among a panel of 12 cytokines, IL-6 and TNF-α seem to be the only cytokines with a relevant role in the diagnosis of sepsis and that their association with PCT leads to a posttest probability comparable to that achieved by PCT and MR-proADM combination." (PMID 26635427, 2015). "It is believed that because this role in the inflammatory process results in severe clinical conditions of sepsis, TNF-α may have a direct correlation with the severity of sepsis and the mortality rate during the development of sepsis in newborns at risk for infections." (PMID 25614712, 2014). "Both sepsis and malaria researchers have shown that injecting TNF, the prototype inflammatory cytokine, increased in both diseases, causes hyperlactataemia, and blood lactate levels in severe malaria have proved to correlate closely with levels of both TNF and interleukin-1." (PMID 17029647, 2006). "LPS-treated mice in the sepsis/induction model group had considerably greater expression of IL-1β and TNF-α within kidney tissues than untreated controls." (PMID 41585603, 2026). "Activation of the NF-κB signaling pathway in sepsis plays a crucial role in the expression of TNF-α, IL-8, and MMP-8, which can further exacerbate the condition." (PMID 42294010, 2026). "Concurrently, HLA‐DR expression in monocytes or AMs from patients with sepsis was positively correlated with TNF‐α and lactate synthesis after LPS treatment in vitro." (PMID 41178622, 2026). "All three sepsis subgroups showed significantly elevated levels of TNF-α, IL-10, HBP and higher APACHE-II scores compared with the control group (all P < 0.05)." (PMID 41737161, 2026). "L-carvone therapy (at low, moderate, and high doses) led to markedly lower kidney IL-1β expression and TNF-α concentrations than observed after sepsis/LPS induction." (PMID 41585603, 2026). "Inflammatory mediators were markedly increased in sepsis (TNF-α, IL-6, HMGB1, TLR-4, and NF-κB; all p < 0.001 vs. Control) and significantly downregulated by pioglitazone (p < 0.01, p < 0.001, p < 0.001, p < 0.01, p < 0.01 vs. CLP + Saline, respectively)." (PMID 41899201, 2026). "This process triggers the release of IL-6, IL-1β, and TNF-α, which drive systemic inflammation, sepsis, septic shock, and disseminated intravascular coagulation (DIC)." (PMID 41521316, 2026). "During sepsis, excessive immune system activation results in the overproduction and imbalance of pro-inflammatory cytokines and mediators, including tumor necrosis factor-alpha (TNF-α), interleukins 1 and 6 (IL-1, IL-6), and reactive oxygen species (ROS)." (PMID 41614895, 2026). "Serum levels of TLR2, TLR4, TLR9, IL-1β, IL-6, IL-8, IL-10, TNF-α and IFN-γ were quantified by enzyme-linked immunosorbent assay at the time of sepsis diagnosis." (PMID 41846925, 2026). "Cardiac impairment in patients with sepsis involves cytokines (e.g., TNF-α and IL-6) that disrupt calcium homeostasis, mitochondrial function, and contractility while inducing nitric oxide overproduction, which reduces myocardial responsiveness." (PMID 41521316, 2026).
Sepsis (continued). "Sleep interruption also increased the levels of serum cytokines (including IL-23 before sepsis was induced, and IL-6, TNF-α, MCP-1, and IL-10 after sepsis), and amplified macrophage cytokine production ex vivo." (PMID 42257268, 2026). "In vivo, azaserine treatment in cecal ligation and puncture-induced sepsis reduced IL-10, increased TNF-α, and elevated bacterial burden." (PMID 41756441, 2026). "Sepsis is initiated by the host immune response and excessive inflammation, leading to the release of pro‐inflammatory cytokines such as IL‐1β, IL‐6, and TNF‐α." (PMID 41551210, 2026). "Cell-cell communication analysis identified TNF signaling as a sepsis-specific pathway, in which cDC1 functions as a critical mediator predominantly via the TNF-TNFRSF1B axis." (PMID 42099630, 2026). "All doses of carvone substantially ameliorated proinflammatory cytokine amounts (IL-1β gene expression and TNF-α levels), in contrast to the sepsis/induction model." (PMID 41585603, 2026). "GSK-J4 has demonstrated anti-inflammatory efficacy in various preclinical models, including colitis, arthritis, and sepsis, by downregulating IL-6, IL-17, and TNF-α, as well as attenuating inflammasome activation." (PMID 40801194, 2025). "The initiation of NF-κB activation is controlled by the phosphorylation of IκB-α, leading to its degradation and, consequently, upregulation of inflammatory cytokines, including TNF-α, IL-1β, and IL-6, which are considered hallmarks of sepsis." (PMID 39940359, 2025). "Sepsis-induced hyperinflammation is primarily driven by TNF-α, IL-6, and IL-1β, whose plasma levels negatively correlate with survival in patients." (PMID 41157235, 2025). "In sepsis, microglia become hyperactivated, releasing large amounts of pro-inflammatory cytokines (TNF-α, IL-1β) and chemokines (MCP-1)." (PMID 40823184, 2025). "In the LPS-induced sepsis model, blocking α2-AR can suppress the expression of myocardial TNF-α and iNOS, reduce apoptosis, and improve cardiac dysfunction." (PMID 40520010, 2025). "To explore the modulation of the immune system with formoterol-enhanced mitochondria, we examined the levels of TNF-α expression in an in vitro sepsis model induced by LPS." (PMID 40299515, 2025). "In previous reports, LPS induction exhibited an increase in cytokine levels (IL-1β, TNF-α and IL-8), activating the inflammatory pathway indicating sepsis." (PMID 41020892, 2025). "Toxins generated in the host during the progression of sepsis activate macrophages, leading to the release of various inflammatory cytokines such as IL-1, IL-6, IL-8, and tumor necrosis factor-alpha (TNF-α), mediated through MAPK and NF-κB pathways." (PMID 41517447, 2025). "In a mouse sepsis model, disulfide effectively reduced mortality and decreased the levels of inflammatory cytokines such as IL-1β, TNF, and IL-6 in serum." (PMID 41041277, 2025). "Sepsis patients with TNF-α production below 200 ng/L in LPS-stimulated monocytes are considered to be in an immunosuppressive state." (PMID 39910395, 2025). "The results showed that LPS injection significantly increased the levels of proinflammatory cytokines IL‐1β, IL‐6, and TNF‐α, confirming successful sepsis induction." (PMID 39836501, 2025). "By inhibiting nuclear factor kappa B (NF-κB) signaling, aspirin reduces the production of pro-inflammatory cytokines such as TNF-α and IL-1, mitigating the excessive inflammatory response seen in sepsis." (PMID 40299932, 2025). "In the mouse model of sepsis, inhibition of caspase-1 can provide neuroprotection by reducing microglial activation and attenuating serum and brain expression of IL-1β and TNF-α." (PMID 39473252, 2025). "Liver injury in sepsis often involves complex pathological mechanisms, including cytokine storms (e.g., TNF-α, IL-6), microcirculatory disturbances, endotoxin assault, and cholestasis." (PMID 41378216, 2025).
Sepsis (continued). "In contrast, the treatment group exhibited a statistically significant decrease in the expression levels of IL-6 (***P<0.001) and TNF-α (**P<0.01) compared to the sepsis group." (PMID 40822580, 2025). "In our polymicrobial sepsis model, at 2 hours post-infection, we found that fluoxetine-pretreated mice had equivalent induction of TNFα and IL-6 and significantly higher levels of serum IL-1β compared to vehicle-treated infected mice." (PMID 39951524, 2025). "The inflammatory environment in septic patients is highly complex, involving a combination of pro-inflammatory cytokines associated with the systemic inflammatory response characteristic of sepsis (e.g., IL-1β, IL-6, TNF-α, and interferon-γ)." (PMID 40950553, 2025). "MALAT1 depletion is responsible for the sepsis inflammatory response by inhibiting the expressions of IL-6 and TNF-α and the NF-κB signaling pathway by upregulating miR-150-5p." (PMID 40041174, 2025). "Because the proinflammatory cytokine TNFα is upregulated in sepsis, the use of anti-TNF agents should have contributed to the control of sepsis." (PMID 40699834, 2025). "In sepsis, the severe systemic inflammatory response, known as cytokine storm, involves the excessive release of inflammatory cytokines such as TNF-α and IL-1α into the bloodstream." (PMID 40725160, 2025). "The characteristic manifestation of sepsis patients is a significant increase in TNF-α levels in circulation." (PMID 40520010, 2025). "A significant increase in TNF-α was observed in the sepsis control group at both the 5th and 10th hours compared to the sham group, indicating a sustained inflammatory response to LPS." (PMID 40566580, 2025). "Mitochondrial transplantation conducted one hour after CLP showed a tendency towards reducing TNF-α, IL-1β, and IL-6 levels compared to the Sepsis group." (PMID 40584438, 2025). "The hyperinflammatory phase in sepsis is characterized by the excessive and uncontrolled release of pro-inflammatory cytokines, such as interleukin-6 (IL-6) and tumor necrosis factor-alpha (TNF-α)." (PMID 40563999, 2025). "Tumor necrosis factor-alpha (TNF-α) and interleukin-6 (IL-6) are key mediators of organ dysfunction in sepsis." (PMID 40558557, 2025). "TNF-α is highly expressed in the host and plays an important role in the early inflammation stages of sepsis." (PMID 40529149, 2025). "LncRNA HOTAIR also elevates tumor necrosis factor-alpha (TNF-α) expression by activating the NF-κB pathway in the cardiomyocytes of an LPS-induced sepsis mouse model." (PMID 39067063, 2025). "Compared with the SIRS cohort, Sepsis_D patients exhibited higher levels of Calprotectin (p = 0.0072), Azurocidin (p < 0.0001), IL-4 (p = 0.0112), IL-8 (p = 0.0015), IL-10 (p = 0.0007), TNF-α (p = 0.0198), and IL-35 (p < 0.0001)." (PMID 41301767, 2025). "During sepsis, exosomes contribute to the progression of inflammation by carrying proinflammatory cytokines (such as IL-1β, IL-6, TNF-α) and activating Toll-like receptors (TLR2, TLR4, TLR7) in immune cells." (PMID 41268545, 2025). "In the context of sepsis, inflammatory factors such as tumor necrosis factor-α (TNF-α) and interleukin-1β (IL-1β) modulate HIF-1α expression by activating the NF-κB pathway." (PMID 40887582, 2025). "For instance, the production of tumor-necrosis factor alpha (TNF-α) in the peritoneum was found to be 16 times higher than in the blood using a CLP-induced sepsis model." (PMID 40852709, 2025). "Toll-like receptors (TLRs) are commonly activated receptors in sepsis, leading to the activation of NF-κB and the subsequent release of inflammatory factors, such as TNF-α, IL-1β, IL-6, and IL-18." (PMID 41311552, 2025). "These biological processes are fundamental to sepsis progression, where uncontrolled inflammatory signaling drives the release of cytokines (e.g., interleukins and TNF-α) and programmed cell death contributes to immune cell depletion and organ failure." (PMID 40362669, 2025).
Sepsis (continued). "The peripheral blood inflammatory markers in patients with sepsis are the primary outcome measures of this study, including IL-6, TNF-α, and CRP." (PMID 41195185, 2025). "Lowers TNF-α and IL-1β serum levels, serves as a diagnostic and prognostic tool, and neutralizes TREM-1 while activating monocytes in sepsis patients." (PMID 41226426, 2025). "In sepsis animal models treated with autophagy activators, the concentrations of inflammatory cytokines such as IL-1β and TNF-α in the serum can increase several times or even more compared to the untreated group." (PMID 40766066, 2025). "Acute lung injury (ALI), caused by both infectious and non-infectious sources such as severe trauma, hyperoxia, and sepsis, is characterized by dysregulated inflammatory responses, including massive release of cytokines (e.g., TNF-α, IL-1β, IL-6, and IL-8)." (PMID 41394141, 2025). "Macrophages drive the inflammatory response in the early stages of sepsis by releasing pro-inflammatory cytokines such as TNF-α and IL-6." (PMID 40124361, 2025). "TNF is a key pro-inflammatory cytokine in sepsis and is significantly involved in SAKI by inducing inflammatory responses, endothelial damage, and tubular cell injury." (PMID 40166075, 2025). "In the context of sepsis, activation of these TLRs triggers the synthesis and release of various cytokines from immune cells, including TNFα, IL-6, and IL-12, driving the excessive inflammatory response." (PMID 39968295, 2025). "In the early stage of sepsis, cytokines like tumor necrosis factor (TNF), interleukin-1β (IL-1β), and interleukin-6 (IL-6) mediate the inflammatory reaction, initiating the systemic inflammatory response syndrome (SIRS)." (PMID 40129981, 2025). "When administered clinically, it has been reported to inhibit excessive inflammatory responses (such as reducing TNF-α and IL - 6 levels) and alleviate the “inflammatory storm” in sepsis." (PMID 41031112, 2025). "We subsequently sought to identify key pro-inflammatory mediators involved in sepsis, including TNF-α, IL-6, and the NLRP3 and RAGE signalling pathways." (PMID 41315622, 2025). "Lipopolysaccharide (LPS) induces the production of TNF‐α in cardiomyocytes, which leads to myocardial depression during sepsis." (PMID 40497340, 2025). "In this context, the IL-18/TNF-α ratio has emerged as a robust predictor of clinical severity in sepsis, further underscoring IL-18 as both a biomarker and a potential therapeutic target." (PMID 41300951, 2025). "These insights emphasize the complex interplay of oxidative stress, thiol-disulfide homeostasis, and key inflammatory mediators such as IL-40 and TNF-α in sepsis pathogenesis." (PMID 41196905, 2025). "In this study, we used TNFα at concentrations of 5 and 10 ng/mL to stress cardiomyocytes, simulating the pro-inflammatory environment observed during sepsis." (PMID 40801652, 2025). "Sepsis-induced cholestasis, common in critical illness, is mediated by cytokines such as TNF-α, IL-1β, and IL-6, which disrupt bile transport, leading to intrahepatic cholestasis and raised conjugated bilirubin, ALP, and GGT." (PMID 40228343, 2025). "Hyperactivation of the immune system during sepsis leads to the massive release of pro-inflammatory cytokines such as tumor necrosis factor- α (TNF- α), interleukin-6 (IL-6), and interleukin-1 β (IL-1 β)." (PMID 40276499, 2025). "An animal study reported reduced serum interleukin-6 (IL-6), high mobility group protein B1 (HMGB)-1, and tumor necrosis factor-α(TNF-α) levels but increased interleukin-10 (IL-10) levels in the group given esmolol compared with the sepsis group." (PMID 40522976, 2025).